CMPK2 (cytidine/uridine monophosphate kinase 2)
Diseases named in the same sentence as CMPK2 in open-access papers (continued):
Sharing a sentence is not in itself a finding about the gene and the disease.
spinal cord injury (1 paper, 2022). Penetrating and non-penetrating injuries to the spinal cord resulting from traumatic external forces (e.g., WOUNDS, GUNSHOT; WHIPLASH INJURIES; etc.). "This study aimed to evaluate the expression of cytosine monophosphate kinase 2 (CMPK2) and activation of the NLRP3 inflammasome in rats with spinal cord injury (SCI) and to characterize the effects of electroacupuncture on CMPK2-associated regulation of the NLRP3 inflammasome." (PMID 35401582, 2022).
Stroke (1 paper, 2025). Sudden impairment of blood flow to a part of the brain due to occlusion or rupture of an artery to the brain. "Cytidine/uridine monophosphate kinase 2 (CMPK2), a key enzyme for mtDNA replication, is upregulated in the peripheral blood of stroke patients, and its expression correlates with infarct volume." (PMID 40244116, 2025).
infection (21 papers, 2019 to 2026). The state of being infected such as from the introduction of a foreign agent such as serum, vaccine, antigenic substance or organism. "One of the early and highly expressed ISGs in macrophages following infection is the mitochondria-associated kinase cytidine monophosphate kinase 2 (CMPK2)." (PMID 36451821, 2022). "Since infections with flaviviruses are known to trigger oxidative stress and hence affect cellular metabolism and viral replication, we examined whether CMPK2 expression is linked to elevated mitochondrial reactive oxygen species (mtROS) formation." (PMID 37075076, 2023). "CMPK2 was also upregulated in Atlantic salmon in response to infection with the monogenean parasite Gyrodactylus salaris and after injection with the immunostimulants LPS and Poly (I:C)." (PMID 38803570, 2024). "The recent developments on the importance of mitochondrial physiology in host cell infection responses directed our attention to the mitochondria-associated ISG, CMPK2, which was highly induced following Mtb infection of macrophages." (PMID 36451821, 2022). "Infected THP1 macrophages showed a steady increase in CMPK2 expression from 15-fold by 6 h and attaining peak levels of ~100-fold by 12 h and thereafter maintained even at 24 h of infection to greater than 80-fold." (PMID 36451821, 2022). "Given the critical role of pro-inflammatory cytokines in the macrophage response to infection, we compared the levels of TNFα and IL1β in the NT and CMPK2 knockdown (KD) macrophages in response to Mtb infection." (PMID 36451821, 2022). "CMPK2, known as cytidine/uridine monophosphate kinase 2, was a vital factor for innate immunity and infection." (PMID 35795789, 2022). "Finally, infections with DENV have been found to induce the production of mtROS leading to inflammasome activation in THP-1 cells which is suppressed in THP-1 CMPK2-KO cells." (PMID 37075076, 2023). "In zebrafish, overexpression of CMPK2 resulted in a decrease of spring viremia of carp virus (SVCV) while knockdown of CMPK2 in SVCV-infected cells showed a significant increase in SVCV demonstrating an antiviral effect against SVCV infection." (PMID 37075076, 2023). "While infection-induced inflammation for restricting pathogens is regulated, our observation of a total dysregulation of basal inflammation by bidirectional alteration of CMPK2 expression only highlights the critical role of this gene in mitochondria-mediated control of inflammation." (PMID 36451821, 2022). "Two of these identified ISGs, CMPK2 and TRIM22, modestly inhibit EBOVΔVP30 infection in NHSK-1-VP30 cells." (PMID 41472248, 2025). "We identified important genes DE in both our in vitro and in vivo infection models consistent with previous studies, namely, TLR3, IFIH1 (MDA5), SOCS1, OASL, DDX60, STAT1, MX1, CMPK2, LY96 (MD-2), STAT1, STAT2, TRIM25, IRF7, and IFIT5." (PMID 38675946, 2024). "Shared genes upregulated with a higher log2 fold change in B/Victoria infection included known anti-viral proteins IFIT1-3, IFITM1, MX2, IFI44L and ISG15 along with mitochondrial-related gene CMPK2." (PMID 37766362, 2023). "In line with our previous study on the robust induction of type I IFN response in Mtb-infected macrophages, we show that CMPK2, an ISG, is highly induced immediately following infection and is rapidly regulated to baseline levels in human macrophages." (PMID 36451821, 2022). "In the present study, chicken CMPK2 was cloned and characterized, and its potential role upon AIV H9N2 infection has been assessed." (PMID 35633731, 2022). "For the interferon regulated genes, Ct infection induced a significant increase in the MX1 and MX2 mRNA fold change (between ~2 and 3.5) at 12, 24 and 36 hpi, while CMPk2 mRNA fold change increased between 36 and 48 hpi to ~2.6 and 2, respectively." (PMID 34684219, 2021). "EBV primary infection and reactivation lead to a coordinated upregulation of RSAD2 and CMPK2." (PMID 41676616, 2026).
infection (continued). "The identification of CMPK2 and ZBP1 as central hub genes highlights their potential roles in coordinating mitochondrial stress responses and regulated cell death mechanisms during the early containment phase of infection." (PMID 41465783, 2025). "CMPK2 (KME = 0.943) is a mitochondria-localized ISG that couples TLR/IFN signals to mtDNA synthesis and NLRP3 inflammasome activation in macrophages, aligning with inflammatory injury mechanisms in infection." (PMID 41465783, 2025). "CMPK2 and TRIM22 also modestly reduced infection, indicating that these proteins may have anti-EBOV capabilities and should be further evaluated in future studies." (PMID 41472248, 2025). "Two mRNAs were down-regulated in all treatment groups at the later time points post-infection, namely, CNTNAP1 and NR4A1, while twenty mRNAs were up-regulated in all later time point treatment groups, including IFI6, LY6E, MX1, OASL, STAT1, and CMPK2." (PMID 38675946, 2024). "APOL1 and CMPK2 are mainly induced by interferon and proinflammatory cytokines, and LGALS9 is widely expressed in cells and immune system tissues and plays a major role in the inflammatory response and immune response against infection." (PMID 37112994, 2023). "In addition, PARP12, TAP1, CMPK2 and ADAR, which are crucial to restrict RNA virus replication, e.g. DENV、HIV、ZIKV, also upregulated in the early stages of HuB20 infection, indicating multiple antiviral responses was involved in this stage." (PMID 36544767, 2022). "In contrast, infection of ultraviolet-inactivated PEDV did not alter CMPK2 expression." (PMID 36930652, 2023). "However, we could not rule out the possibility that CMPK2 inhibits other early infection stages such as virus entry or membrane fusion." (PMID 37075076, 2023). "While these pro-inflammatory cytokines were not increased, Ct infection of pOECs did lead to a significant increase in the mRNA expression of the interferon regulated genes MX1, MX2, and CMPK2." (PMID 34684219, 2021). "At the earlier time points post-infection, we did not observe any overlap with down-regulated mRNAs; however, 27 up-regulated mRNAs were common to all early treatment groups, including TLR3, IFIT5, IFIH1 (MDA5), MX1, RSAD2 (viperin), CMPK2, SOCS1, and SCNN1D." (PMID 38675946, 2024). "IFN-I treatment suppressed ZIKV replication significantly in NT HFF cells at 24 hours post infection (hpi), but notably there was no decrease in ZIKV titers in IFN-I-treated CMPK2-KO HFF cells, suggesting that CMPK2 is required to facilitate IFN-I-mediated restriction of ZIKV replication." (PMID 37075076, 2023).
tumor (8 papers, 2020 to 2025). "Our results indicated a decrease in CMPK2 expression in tumor cells surrounding blood vessels, especially in animals administered 13 mg/kg of BA." (PMID 39821858, 2025). "Again, B3 revealed mild cytoplasmic Ki67 and CMPK2 expressions in tumor cells around blood vessels, along with moderate GFAP expression in astrocytes surrounding the tumor." (PMID 39821858, 2025). "Besides, moderate intracytoplasmic Ki67 and CMPK2 expressions were detected in tumor cells around blood vessels in B2 group." (PMID 39821858, 2025). "Targeting CMPK2 could disrupt tumor proliferation and modulate the immune microenvironment, offering a multifaceted therapeutic approach." (PMID 39821858, 2025). "Immunohistochemical and immunofluorescence staining showed modulation of intracytoplasmic Ki67, cytoplasmic CMPK2, and GFAP expressions in tumor cells post-BA treatment." (PMID 39821858, 2025). "Although the initial CCM screen evaluated associations with a gene signature of immune activity, including TLS formation, the emerging CCMs covered genes that are expressed by tumor cells (e.g., RSAD2, CMPK2) and stromal fibroblasts (e.g., SUCNR1) as well as immune cells (e.g., POU2F2)." (PMID 40723216, 2025). "CMPK2, a key gene involved in DNA synthesis, plays an essential role in cell growth and is found to be elevated in tumor cells while not in normal brain cells." (PMID 39821858, 2025). "RT-qPCR analysis revealed that the lncRNA levels of HDAC9, CMPK2, MINDY4B were up-regulated in the ALV-J induced tumor livers (positive group) compared to the normal livers in the negative group, whereas lncRNA levels of ATOH8 and LOC100859478 were down-regulated in the positive group." (PMID 35529873, 2022). "CMPK2 is a key gene in DNA synthesis, and is therefore essential for cell growth which is elevated in tumor cells but not in normal brain cells." (PMID 32362913, 2020). "Direct contributions of CMPK2 and RSAD2 to anti-tumor immune response induction, as opposed to serving as indirect biomarkers of interferon signaling, should be clarified." (PMID 40723216, 2025).
bacterial infection (4 papers, 2021 to 2022). "Since studies in different species indicate an important role of CMPK2 regarding immunomodulatory signaling pathways, especially in association with bacterial infections, this gene was selected as a candidate gene for a potential influence on BDD." (PMID 35832195, 2022). "CMPK2 expression has also been widely used for monitoring to trace inflammation upon bacterial infection with Lyme disease spirochete Borrelia burgdorferi in mice and human." (PMID 35832195, 2022). "CMPK2 has been reported to be able to inhibit viral and bacterial infection, including SVCV, Dengue virus (DENV), Duck Tembusu virus (DTMUV), HIV-1 and Aeromonas hydrophila CCL1." (PMID 35633731, 2022). "Further, CMPK2 in fish was shown to be involved in host innate immunity and plays a protective role in antimicrobial responses during bacterial infections." (PMID 34705862, 2021). "Multiple tissues exist for CMPK2 expression, and bacterial infection could upregulate CMPK2 expression in a time-dependent manner." (PMID 35795789, 2022).
cancer (4 papers, 2022 to 2025). A tumor composed of atypical neoplastic, often pleomorphic cells that invade other tissues. "Regarding pyrimidine metabolism, the upregulation of CMPK1, CMPK2, CTPS2, CAD, DHODH, and UMPS suggests a role in supporting placental growth under stress, reflecting their established functions in cancer cell proliferation." (PMID 40825832, 2025). "There is also evidence that CMPK2 and PDE4B, which are immune checkpoint proteins in cancers, inhibit cell proliferation and induce apoptosis." (PMID 35957812, 2022). "Given that CMPK2 and CTPS might also have a role in the EMT phenotypes, we analyzed their correlation with EMT status by using the public gene expression databases, Cancer Cell Line Encyclopedia and Sanger/Massachusetts General Hospital GDSC, which encompass gene expression of 130 NSCLC cell lines." (PMID 39030877, 2024).
brain disorder (1 paper, 2022). A disease affecting the brain or part of the brain. "Collectively, the strong expression of Cmpk2 in neurons and brain vECs supports that Cmpk2 deficiency may cause brain disorder, including brain calcification." (PMID 36443312, 2022).
CMPK2 also shares sentences with these, for which no sentence is quoted: acute respiratory distress syndrome (2 papers); allergic rhinitis (1); Arthritis (1); asthma (1); avian disease (1); calcification (1); co-infection (1); HIV-1 infection (1); lymphoblastic leukemia (1); neurodevelopmental disorder (1); Obesity (1); Oral ulcer (1); osteoarthritis (1); Parkinson disease (1); prostate carcinoma (1); respiratory diseases (1); rheumatoid arthritis (1); systemic sclerosis (1); type 1 diabetes (1).